MINDY2 (MINDY lysine 48 deubiquitinase 2)
Description:
Hydrolase that can remove 'Lys-48'-linked conjugated ubiquitin from proteins. Binds to polyubiquitin chains of different linkage types, including 'Lys-6', 'Lys-11', 'Lys-29', 'Lys-33', 'Lys-48' and 'Lys-63'. May play a regulatory role at the level of protein turnover.
Synonyms: FAM63B; KIAA1164
Tractability: PROTAC: ubiquitination databases record sites on it.
Gene: Protein-coding gene on chromosome 15 (58,771,117 to 58,861,900, forward strand). Ensembl gene ENSG00000128923.
Subcellular location (Human Protein Atlas): Nucleoplasm
Gene Ontology:
Molecular function: cysteine-type carboxypeptidase activity; cysteine-type deubiquitinase activity; K11-linked polyubiquitin modification-dependent protein binding; K48-linked deubiquitinase activity; K48-linked polyubiquitin modification-dependent protein binding; K6-linked polyubiquitin modification-dependent protein binding; K63-linked polyubiquitin modification-dependent protein binding
Cellular component: nucleoplasm
Genetic constraint (gnomAD): Loss-of-function variants: 40 observed, 51.18 expected, observed/expected ratio (o/e) 0.78, 90% interval 0.61 to 1.02. The upper end of that interval is the gene's LOEUF score, 1.02, which puts it in group 4 of 6, group 1 being the genes least tolerant of losing a copy. Missense variants: 784 observed, 696.71 expected, observed/expected ratio (o/e) 1.13, 90% interval 1.06 to 1.19. Synonymous variants: 339 observed, 287.71 expected, observed/expected ratio (o/e) 1.18, 90% interval 1.08 to 1.29.
Homologues: Orthologues: macaque MINDY2 (96% identical), dog MINDY2 (91% identical), rabbit MINDY2 (87% identical), pig MINDY2 (85% identical), mouse Mindy2 (82% identical), rat Mindy2 (77% identical), guinea pig MINDY2 (74% identical), zebrafish mindy2 (61% identical), tropical clawed frog mindy2 (42% identical), Caenorhabditis elegans Y55F3AM.9 (21% identical). Paralogues in human: MINDY1 (40% identical).
Diseases named in the same sentence as MINDY2 in open-access papers:
MINDY2 is named in the same sentence as 10 diseases in open-access papers, as found by Europe PMC text mining. Sharing a sentence is not in itself a finding about the gene and the disease. The quoted sentences say what the papers report.
pancreatic cancer (2 papers, 2023 to 2024). "MINDY Lysine 48 Deubiquitinase 2 (MINDY2) interacts with and deubiquitinates ACTN4, stabilizes ACTN4, and activates the PI3K/AKT/mTOR signaling pathway to promote pancreatic cancer proliferation and metastasis." (PMID 39115875, 2024).
tumor (2 papers, 2023). "The results showed that the volume and weight of tumor formation in nude mice were significantly higher than those in the control group after the upregulation of MINDY2; opposite result was obtained after the downregulation of MINDY2." (PMID 37207150, 2023). "In addition, the immunohistochemical results of tumor tissue showed that after the stable up-regulation of MINDY2, the staining intensity and positive ratio of MINDY2 in tumor tissue were higher than those in the control group." (PMID 37207150, 2023). "Also, MINDY2 expression correlated with T-stage, N-stage, tumor grade, and cancer stage of PC." (PMID 37207150, 2023). "Patients receiving intensive chemotherapy of their NBT showed significantly reduced tumor tissue expression of USP24, USP34, MINDY2, USP8, JOSD1, USP52, and USP12 when compared to the observation group." (PMID 37892185, 2023). "Then we further analyzed and found that MINDY2 was positively correlated with pro-cancer factors such as EMT, inflammatory response, ECM-related genes, angiogenesis, and tumor inflammatory features in PC, and negatively correlated with DNA repair capacity." (PMID 37207150, 2023). "We found that MINDY2 was expressed elevated in PC at mRNA and protein levels and correlated with prognostic indicators such as OS, PFS, DSS, T stage, N stage, tumor grading, and tumor stage in patients." (PMID 37207150, 2023). "The Tumor Immune Dysfunction and Exclusion (TIDE) algorithm predicted the immunotherapeutic response of MINDY2 in PC and discovered that the higher the expression of MINDY2, the better the response of PC to immune checkpoint inhibitors." (PMID 37207150, 2023).
cancer (1 paper, 2023). A tumor composed of atypical neoplastic, often pleomorphic cells that invade other tissues. "Thus, ACTN4 is essential in the cancer-promoting process of MINDY2." (PMID 37207150, 2023). "To further investigate the cancer-promoting mechanism of MINDY2 in PC, we identified ACTN4 as an interacting protein of MINDY2 by immunoprecipitation, mass spectrometry, and immunofluorescence co-localization." (PMID 37207150, 2023). "The results demonstrated that the mRNA and protein levels of MINDY2 expression were higher in cancer tissues than in nearby normal tissues." (PMID 37207150, 2023).
MINDY2 also shares sentences with these, for which no sentence is quoted: bipolar disorder (3 papers); schizophrenia (2); breast carcinoma (1); epilepsy (1); infection (1); Obesity (1); type 2 diabetes (1).